PCSK9 (proprotein convertase subtilisin/kexin type 9)
Diseases named in the same sentence as PCSK9 in open-access papers (continued):
Sharing a sentence is not in itself a finding about the gene and the disease.
myocardial infarction (150 papers, 2008 to 2026). Gross necrosis of the myocardium, as a result of interruption of the blood supply to the area, as in coronary thrombosis. "The trial provides substantial mechanistic evidence supporting the early administration of PCSK9 inhibitors following acute myocardial infarction (AMI) to reduce residual atherosclerotic risk." (PMID 41010649, 2025). "Regarding cardiovascular events, although all the agents decreased the risk of major adverse cardiovascular events and myocardial infarction, PCSK9 inhibitors were found to be the most effective treatment agent compared with either placebo or statins." (PMID 37881090, 2024). "On the other hand, a Swedish analysis showed that PCSK9 inhibitors are cost-effective in the secondary prevention of myocardial infarction in combination therapy for very high-risk patients." (PMID 38988669, 2024). "PCSK9 associated with the occurrence of myocardial infarction, cardiac arrest, cardiogenic shock, life-threatening arrhythmia, or stroke only in women, whereas it associated with death only in men." (PMID 37620933, 2023). "PCSK9 mAbs were associated with a 20% lower risk of myocardial infarction, a 22% lower risk of ischemic stroke, and a 17% lower risk of coronary revascularization." (PMID 37623860, 2023). "The search was performed using keywords such as PCSK9 inhibitors, alirocumab, evolocumab, cardiovascular risk, acute coronary syndrome, and myocardial infarction." (PMID 36895542, 2023). "Comprehending the efficiency of PCSK-9 inhibitors in lowering CV events such as heart attacks, strokes, and deaths from CV causes was the primary expected outcome." (PMID 37937036, 2023). "Consistently, patients in the Chinese Han population with the PCSK9 R93C variant (PCSK9 loss-of-function mutant) have a lower risk of myocardial infarction." (PMID 36970356, 2023). "Regardless of the specific underlying mechanism, upregulated PCSK9 is unfavorable to the recovery of myocardial infarction." (PMID 36970356, 2023). "A recent study reported that the PCSK9 R93C variant was associated with a 60% lower risk of premature myocardial infarction in the Chinese Han population." (PMID 36142332, 2022). "In CVDs, there is a piece of evidence that PCSK9 is related to myocardial infarction caused by platelet activation through CD36 while these factors are found in various organs and behave differently." (PMID 34307504, 2021). "To this, we can add the recent myocardial infarction subgroup analysis from the Further Cardiovascular Outcomes Research With PCSK9 Inhibition in Subjects With Elevated Risk (FOURIER) study (evolocumab vs standard care)." (PMID 32596859, 2020). "PCSK9 plasma levels were associated with the severity of coronary lesions in patients with acute coronary syndrome and myocardial infarction." (PMID 31672148, 2019). "Plasma PCSK9 levels have been reported to be elevated in patients with acute myocardial infarction and associated with severity of CAD." (PMID 27658826, 2016). "A genome-wide association study further bolstered the importance of PCSK9 by establishing a linkage between a single nucleotide polymorphism at a locus near PCSK9 with early-onset myocardial infarction." (PMID 24278757, 2012). "In human studies in adults, serum PCSK9 levels are positively associated with acute myocardial infarction and high-sensitivity C-reactive protein levels, whereas PCSK9 inhibitors such as evolocumab or alirocumab reduce the risk of recurrent ischemic cardiovascular events." (PMID 38440108, 2024). "In addition to LDL-C lowering, PCSK9 inhibitors have been shown to decrease the incidence of cardiovascular events, including myocardial infarction and strokes, in high-risk patients." (PMID 38919858, 2024).
myocardial infarction (continued). "For example, mAbs targeting proprotein convertase subtilisin/kexin type 9 (PCSK9) control cholesterol metabolism, whereas anti-IL-1β mAbs aid in decreasing inflammation and minimizing the risk of recurring events in patients with prior myocardial infarctions." (PMID 39390211, 2024). "In addition, CD36-mediated thrombosis and NLRP3 inflammasome-mediated autophagy are both associated with the effect of PCSK9 on myocardial infarction prognosis." (PMID 36970356, 2023). "Therefore, the level of plasma PCSK9 is positively related to the occurrence risk and the severity of myocardial infarction." (PMID 36970356, 2023). "This animal model may contribute to future studies aiming to elucidate the mechanisms underlying the association among risk factors for myocardial infarction involving PCSK9 and platelet activation." (PMID 37892538, 2023). "However, PCSK9-mAb use was associated with a 20% lower risk of myocardial infarction (MI), a 22% lower risk of ischemic stroke, and a 17% lower risk of coronary revascularization (all statistically significant)." (PMID 35900635, 2022). "Evolocumab is a recently FDA-approved proprotein convertase subtilisin/kexin type 9 inhibitor (PCSK9i) that reduces the risk of myocardial infarction, stroke, and coronary revascularization in individuals with established atherosclerotic cardiovascular disease." (PMID 34262805, 2021). "Clinical data support that notion in that PCSK9 inhibition is associated with reductions in the incidence of myocardial infarction, stroke, and coronary revascularization and an improvement of endothelial function in subjects with increased cardiovascular risk." (PMID 33262707, 2020). "PCSK9 plasma levels have been associated with obstructive coronary lesions in patients with acute coronary syndrome and myocardial infarction as well as with subclinical coronary atherosclerosis and imaging markers of atherosclerotic risk even if in some reports this relationship is not so clear." (PMID 31672148, 2019). "However, few studies have comprehensively evaluated the association of plasma PCSK9 with the pathogenesis of acute myocardial infarction till now." (PMID 30816133, 2019). "The elevated risk of severe cardiovascular events in patients with myocardial infarction with ST segment elevation (STEMI) with high PCSK9 levels and DM may be due to the substantial association between PCSK9 and indicators of inflammation and platelet activation." (PMID 37765005, 2023). "Hearts from wild‐type (WT) C57BL/6J mice and PCSK9 knockout (PCSK9−/−) mice were subjected to left coronary artery (LAD) ligation to establish a myocardial infarction model." (PMID 41573336, 2026). "Six weeks postoperation, echocardiographic analysis and Masson staining revealed that inhibiting the increase in PCSK9 expression after myocardial infarction significantly reduced myocardial fibrosis." (PMID 41573336, 2026). "Proprotein convertase subtilisin/Kexin Type 9 (PCSK9) inhibitors are widely used in patients with acute myocardial infarction due to their potent low‐density lipoprotein‐lowering effects." (PMID 41573336, 2026). "The detailed molecular and cellular mechanisms through which PCSK9 regulates cardiac repair after myocardial infarction by inducing platelet activation were observed." (PMID 41573336, 2026). "The PCSK9 R46 L loss-of-function mutation has been associated with lower levels of LDL-cholesterol and a reduced risk of myocardial infarction." (PMID 40870420, 2025). "Here, we systematically reviewed the available scientific evidence of genetic variation on PCSK9 and assessed the efficacy of PCSK9 inhibitors in cardiovascular outcomes, including cardiovascular death, myocardial infarction, and stroke." (PMID 38907775, 2025).
myocardial infarction (continued). "Adding PCSK9 inhibitors to statins is notably beneficial in patients experiencing recent myocardial infarctions with residual multivessel coronary disease, likely due to plaque stabilization, particularly in vulnerable thin-cap fibroatheroma." (PMID 40351996, 2025). "A gain-of-function mutation in the PCSK9 gene has been recognized in patients with familial hypercholesterolemia, which is correlated with the increased incidence and mortality rate of myocardial infarction (MI)." (PMID 40076547, 2025). "A lowered LCBI after PCSK9 inhibitor treatment means plaques are less likely to rupture, decreasing the risk of major adverse cardiovascular events (MACE) like myocardial infarction, stroke, and death." (PMID 41010649, 2025). "Based on these insights, several recent and ongoing studies have been employing PCSK9 inhibitors early in the treatment process and off-label for patients with acute myocardial infarction who are receiving percutaneous coronary intervention." (PMID 38817546, 2024). "In patients with acute myocardial infarction, there is a significant increase in PCSK9 expression and increased autophagy in the border zone of the myocardial infarction." (PMID 38886277, 2024). "The impact of PCSK9 inhibitors on endothelial function in heart attack survivors is not yet fully understood." (PMID 39770423, 2024). "The EVOLVE-MI (EVOLocumab Very Early After Myocardial Infarction) trial (NCT05284747) aims to evaluate the impact of PCSK9 inhibition on clinical outcomes following an ACS." (PMID 39150672, 2024). "PCSK9 inhibitors significantly reduced cardiovascular events, heart attacks, and ischaemic strokes compared to statins." (PMID 38988669, 2024). "VCU-AlirocRT was another early PCSK9-inhibitor initiation trial, initiating alirocumab treatment at the time of the myocardial infarction (defined as within the first 24 h of presentation) in 20 patients with LDL > 70 mg/dL." (PMID 39274253, 2024). "Our study provides significant insights into the role of PCSK9 and its inhibitors in the heart, particularly following myocardial infarction." (PMID 39906341, 2024). "The use of a PCSK9 inhibitor in mice reduces the area of myocardial infarction and decreases the excessive activation of the autophagy process." (PMID 38886277, 2024). "In our study, genetic deletion of PCSK9 in mice prevented ventricular rupture and death following experimental myocardial infarction." (PMID 39906341, 2024). "In a model of surgically induced myocardial infarction in rats and mice, there was a significant increase in plasma PCSK9 levels during the acute phase of myocardial infarction, with a peak concentration at 48 h after infarction." (PMID 38886277, 2024). "In 2018, Zufeng Ding’s team highlighted elevated expression of PCSK9 in hypoxic cardiomyocyte and the border zone of a mouse myocardial infarction model, with an induction of autophagy dependent on extracellular PCSK9 concentrations." (PMID 38383373, 2024). "The PACMAN-AMI trial (Effects of the PCSK9 Antibody Alirocumab on CoronaryAtherosclerosis in Patients with Acute Myocardial Infarction) showed a similareffect of alirocumab on plaque composition." (PMID 39484117, 2024). "In the previous reports, PCSK9 and pyroptosis signaling are highly expressed in patients with myocardial infarction." (PMID 37935689, 2023). "A temporary increase in the circulating concentration of PCSK9 and Lp(a) was shown in patients with myocardial infarction (MI)." (PMID 37873789, 2023). "When myocardial infarction occurs, PCSK9 promotes the generation of ROS and activates CD36 in platelets, resulting in microvascular obstruction and enlarged infarct size." (PMID 36970356, 2023).
myocardial infarction (continued). "Subsequently, we show the effect of PCSK9 and its inhibitors on the prognosis of atherosclerotic and myocardial infarction patients." (PMID 36970356, 2023). "It was demonstrated that the cost-effectiveness of PCSK9 inhibition was improved in patients with a recent history of myocardial infarction and high LDL-C levels, which was consistent with the 2019 ESC/EAS guidelines and previous data." (PMID 37547279, 2023). "Higher plasma levels of PCSK9 and hs-CRP lead to an earlier decline in left ventricular ejection fraction in myocardial infarction patients, further increasing the risk of myocardial infarction-induced heart failure (HF) and even death." (PMID 36970356, 2023). "When myocardial infarction develops in mice with PCSK9 knockdown or with PCSK9 inhibitor Pep2-8 treatment, the infarct size is smaller and the autophagy is reduced compared with WT mice." (PMID 36970356, 2023). "PCSK9: proprotein convertase subtilisin/kexin type 9; MI: myocardial infarction; ACS: acute coronary syndrome." (PMID 36895542, 2023). "The development of PCSK9 inhibitors has strengthened this prospect, as demonstrated by their ability to promote cardiac function in a rat model of acute myocardial infarction (AMI)." (PMID 37892538, 2023). "The effect of alirocumab, a PCSK9 inhibitor, on the plaque volume and characteristics were evaluated in the PACMAN-AMI (Effects of the PCSK9 Antibody Alirocumab on Coronary Atherosclerosis in Patients With Acute Myocardial Infarction) randomized trial." (PMID 37008333, 2023). "One week after ligation of the left anterior descending coronary artery in C57BL/6J WT mice, the increased expression of PCSK9 in the zone bordering the infarct area leads to the progression of myocardial infarction." (PMID 36970356, 2023). "Evolocumab (a PCSK9 inhibitor) is a novel lipid-lowering drug that has been shown to decrease the incidence of myocardial infarction and stroke." (PMID 35720337, 2022). "Accordingly, PCSK9 inhibitors were established and found to improve cardiac function in an acute myocardial infarction (AMI) rat model." (PMID 35207479, 2022). "The correlation analysis indicated a significant correlation between PCSK9 expression and cardiac function after myocardial infarction." (PMID 35832650, 2022). "This study aims to investigate the efficacy and safety of in-hospital initiation of PCSK9 inhibitors among patients with acute myocardial infarction (AMI) based on real-world experience." (PMID 36280861, 2022). "Our data suggested that PCSK9 modulated macrophage polarization-mediated ventricular remodeling after myocardial infarction." (PMID 35832650, 2022). "The current use of lipid lowering therapies and the eligibility for proprotein convertase subtilisin/kexin-9 (PCSK9) inhibitors of patients surviving a myocardial infarction (MI) is poorly known." (PMID 31969932, 2020). "In summary, although very few studies have investigated the role of PCSK9 on myocardial infarct size in experimental animal models, it seems that the pharmacological inhibition of PCSK9 results in cardioprotective effects." (PMID 33262707, 2020). "Results from clinical studies have already shown that PCSK9 inhibitors have different effects on type and size of myocardial infarcts." (PMID 33262707, 2020). "By contrast, in the recently reported FOURIER randomized controlled trial, PCSK9-inhibitor therapy that lowered LDL-C levels by about 1.5 mmol/L reduced the rates of both myocardial infarction and IS by about one-quarter over 2 years." (PMID 29020353, 2018). "Meanwhile, PACMAN-AMI is evaluating the effects of PCSK9 inhibition on the morphology of coronary plaque in patients with acute myocardial infarction." (PMID 29850255, 2018). "The first outcome data of the PCSK9 inhibitor evolocumab reported a significant reduction in the composite endpoint (cardiovascular death, myocardial infarction, or stroke) and further outcome data are awaited." (PMID 28439730, 2017).
myocardial infarction (continued). "Therefore, the objective of this study was to investigate and clarify the specific effect of PCSK9 on cardiac repair processes following myocardial infarction." (PMID 41573336, 2026). "This systematic review will address the key questions surrounding the major research objectives: What is the effectiveness of PCSK9 inhibitors in reducing major adverse cardiovascular events, specifically myocardial infarction, stroke, and cardiovascular death, in the statin-intolerant population?" (PMID 40110272, 2025). "Moreover, the use of PCSK9 inhibitors prior to myocardial infarction has been shown to suppress PCSK9 expression, decelerate the process of autophagy, and mitigate myocardial ischemia–reperfusion injury." (PMID 39368019, 2025). "Proprotein Convertase Subtilisin/Kexin type 9 PCSK9 inhibitors (PCSK9i) are a novel class of cholesterol-lowering agents that also offer protection against tissue ischemia by reducing apoptosis, pyroptosis, and myocardial infarct size." (PMID 41009504, 2025). "Early PCSK9 inhibitor therapy significantly reduces the risk of major adverse cardiovascular events, including nonfatal myocardial infarction, cardiogenic death, stroke, hospitalization for recurrent ACS, and coronary revascularization." (PMID 41010649, 2025). "In this work, we profiled hearts of PCSK9-KO mice and tested their fate post myocardial infarction." (PMID 39906341, 2024). "Could a PCSK9 “heart attack” vaccine offer a long-term and cost-effective solution for controlling LDL-C levels?" (PMID 38819987, 2024). "The result demonstrated that patients used PCSK9 inhibitors could reduce myocardial infarction than those who used statins or placebo treatment." (PMID 39259104, 2024). "Following myocardial infarction, however, PCSK9 levels exceed baseline levels by factor 4 to 10 in blood, the infarct and border zone, an effect further amplified by PCSK9-antibody mediated accumulation of PCSK9." (PMID 39906341, 2024). "In addition, high expression of PCSK9 in the border zone of myocardial infarction has been confirmed in animals and humans." (PMID 38886277, 2024). "PCSK9′s role in platelet activation involves promoting reactive oxygen species (ROS) levels and thrombosis, which can lead to arterial clotting disorders like myocardial infarction and ischemic stroke." (PMID 39770423, 2024). "In this single-center, real-world data analysis, after the release of the 2019 European Society of Cardiology/European Atherosclerosis Society guidelines, an increasing number of patients with a recent acute myocardial infarction were initially receiving ezetimibe and PCSK9 inhibitors." (PMID 38517999, 2024). "Another in vitro experiment showed that increasing PCSK9 levels could enhance the transition of cardiac fibroblasts into myofibroblasts, impacting fibrosis post-myocardial infarction." (PMID 39090671, 2024). "Furthermore, this meta-analysis revealed that PCSK9 inhibitors can effectively reduce the occurrence of myocardial infarction and angina when analyzed separately." (PMID 39259104, 2024). "Recently published PACMAN-AMI (Effects of the PCSK9 Antibody Alirocumab on Coronary Atherosclerosis in Patients With Acute Myocardial Infarction) randomized trial has shown that aggressive lipid-lowering leads to degeneration of plaque vulnerability features, including macrophage infiltration." (PMID 36315364, 2023). "The aim of the current study was to identify the predictors of functional and morphological properties of the arterial wall in patients after myocardial infarction and increased Lp(a) levels at the beginning and after treatment with proprotein convertase subtilisin-kexin type 9 (PCSK9) inhibitors." (PMID 37580777, 2023). "When myocardial infarction occurs, the expression level of PCSK9 is also upregulated in the ischemic heart tissue, mostly in the border zone, and hypoxia as well as proinflammatory cytokines may be the key factors that upregulate its expression." (PMID 36970356, 2023).